MTOR (mechanistic target of rapamycin kinase)
Diseases named in the same sentence as MTOR in open-access papers (continued):
Sharing a sentence is not in itself a finding about the gene and the disease.
Alzheimer disease (continued). "We investigated the possible correlation between T14 and p-mTOR s2448 levels by performing a Western blot in midbrain samples from Alzheimer’s disease patients." (PMID 37373106, 2023). "The SGLT2i drugs promote the loss of glucose in the urine, which can impact the mTOR signalling pathway and modulate AMPK activity; and both molecular pathways play a role in cerebral amyloid deposition and development of Alzheimer’s disease." (PMID 37109151, 2023). "A total of 13 KEGG pathways were significantly enriched, including cell cycle, mTOR signaling pathway, autophagy-animal, ribosome, oxidative phosphorylation, thermogenesis, Parkinson's disease, and Alzheimer's disease." (PMID 37213521, 2023). "p70S6K, with its upstream mammalian target of rapamycin (mTOR), has been shown to be involved in learning and memory and participate in the pathophysiology of Alzheimer’s disease (AD)." (PMID 36624510, 2023). "Previous research indicated that the levels of phosphorylated mTOR and p70S6 kinase exhibit a decline in ischemic brain injury and Alzheimer’s disease." (PMID 37631097, 2023). "In HepaRG cells, MC-LR or CYN upregulates oxidative phosphorylation, ribosomal, Parkinson’s disease, Alzheimer’s disease, and mTOR as well as the NAFLD pathway." (PMID 37505679, 2023). "Dactolisib is a dual ATP competitive PI3K and mTOR inhibitor, which has been proven to have certain effects on tumors, inflammatory diseases, polycystic kidney disease, and Alzheimer’s disease." (PMID 36875119, 2023). "Phosphorylated Myc has been detected in brain tissues affected by tauthopathies, including supranuclear palsy, Alzheimer’s Disease (AD) and corticobasal degeneration and has been linked to both Ras/MAPK and PI3K/mTOR pathways." (PMID 37606389, 2023). "p70S6K, together with its upstream mTOR, has received attention as a key modulator in memory and Alzheimer’s disease (AD), the most prevalent neurodegenerative disease characterized by progressive cognitive dysfunction." (PMID 36624510, 2023). "Increased phosphorylation of Akt at S473 and mTOR phosphorylation at S2448 have been observed in the temporal cortex neurons in Alzheimer’s disease." (PMID 35742908, 2022). "Normally, mTOR expression is downregulated in an age-dependent manner, yet the mTOR pathway is hyperactive in both animal models and humans with Alzheimer's disease." (PMID 36465185, 2022). "In Alzheimer's disease, mTOR activation promotes the production and accumulation of amyloid-β in the brain, and this event is linked with a direct inhibition of the autophagy-lysosomal system." (PMID 36388931, 2022). "The activities of mammalian target of rapamycin (mTOR)/ribosomal S6 protein kinase (p70S6K) are elevated in the brains of patients with Alzheimer’s disease." (PMID 35197970, 2022). "In a rat model of Alzheimer’s disease (AD) induced by zinc injection, inhibition of mTOR by rapamycin attenuated zinc-induced tau phosphorylation and elevated levels of oxidative stress, as well as the synaptic impairment and decrease in cognitive function." (PMID 35883796, 2022). "Accordingly, inhibition of mTOR by sirolimus reduces the cognitive deficits and the amyloid-β levels in a mouse model of Alzheimer’s disease, the PDAPP transgenic mouse model." (PMID 35456509, 2022). "In further studies, mice with TREM-2 knockout in Alzheimer’s disease showed decreased mTOR pathway activity, impaired glycolysis and increased neuronal autophagy." (PMID 35669777, 2022). "Additionally, when looking at late effects of mTOR activity, both human and experimental studies indicate a direct and indirect connection between mTOR hyperactivity and formation of abnormally hyperphosphorylated Tau protein, which is associated with Alzheimer’s disease." (PMID 35276811, 2022).
Alzheimer disease (continued). "Treatment with rapamycin or rapalogs in mice with Alzheimer's disease reduces cognitive deterioration, suggesting that inhibitors of mTOR can potentially heal age-related disorders though adverse effects (such as immune system suppression) are inevitable." (PMID 36465185, 2022). "The pathways that were significantly enriched in KEGG of cis effects were oxidative phosphorylation, metabolic pathways, Alzheimer’s disease, Parkinson’s disease and mTOR signaling pathway." (PMID 36352898, 2022). "According to a previous study, FTO, which was found to be highly expressed in brain tissues, participated in Alzheimer’s disease (AD) through its effect on mTOR in AD mouse models." (PMID 35634463, 2022). "Many different signaling pathways, such as Wnt/β-catenin, Notch, ROS/JNK, and PI3K/Akt/mTOR are involved in Alzheimer’s disease and crosstalk between themselves." (PMID 34208692, 2021). "In Alzheimer’s disease patients and mouse models, hyperactive mTOR signaling has been reported in the brain regions affected by the disease." (PMID 34515928, 2021). "In Alzheimer’s disease, the inhibition of mTOR by rapamycin ameliorates the synthesis of β-amyloid and tau protein and improves learning and memory abilities." (PMID 33935683, 2021). "Geniposide was able to increase autophagy and inhibit apoptosis by regulating the function of mTOR in treating Alzheimer's disease." (PMID 34454545, 2021). "The compelling preclinical record reviewed above calls for clinical trials to test rapamycin or other mTOR inhibitors and/or possibly mTORC2 agonists, beginning in patients with Alzheimer's disease." (PMID 34215308, 2021). "However, a fine balance of mTOR activation is essential to prevent neurodegeneration, since mTOR hyperactivation has been associated with an increase in the phosphorylation of tau protein contributing to the formation of neurofibrillary tangles in Alzheimer’s disease." (PMID 34443417, 2021). "A recent study showed that inhibition of the mTOR pathway by rapamycin leads to the downregulation of MMP9 activity in models of Alzheimer's disease and vascular cognitive impairment." (PMID 31183875, 2020). "Meanwhile, earlier research demonstrated an ability of memantine to prevent inhibition of the PI3K/Akt/mTOR pathway in an APP695-overexpressing SH-SY5Y cell model of Alzheimer’s disease." (PMID 33174867, 2020). "In previous studies, mTOR signaling was identified as a critical regulatory pathway in these neurodegenerative disorders, and inactivation of mTOR by rapamycin has been regarded to be a potential therapeutic method in the treatment of Alzheimer’s disease." (PMID 31219803, 2019). "GSEA results showed that samples with deficiency of MTOR, CRISPLD2 or MORF4L1 showed consistent down-regulation in pathways of Alzheimer’s disease, Parkinson’s disease and Huntington’s disease." (PMID 31219803, 2019). "Our laboratory recently demonstrated the disturbance of PI3K/AKT/mTOR axis in DS brain, prior and after the development of Alzheimer Disease (AD)." (PMID 30410750, 2018). "Regarding the pathophysiological association between aging and Alzheimer's disease, the impact of mTOR in Alzheimer's disease has therefore been extensively investigated." (PMID 29992725, 2018). "In the central nervous system, mTOR inhibition demonstrates neuroprotective patterns in aging and Alzheimer’s disease (AD) by preserving mitochondrial function and reducing amyloid beta retention." (PMID 30140223, 2018). "In the same way, it has been proposed that amyloid beta (Aβ) and Tau proteins, involved in the pathogenesis of Alzheimer's disease, increase MTOR signaling pathway." (PMID 29705815, 2018). "The macroautophagic system in neurons is activated partially through the mTOR pathway in prion diseases and Alzheimer’s disease." (PMID 28515679, 2017). "mTOR, the main downstream signaling factor in the Akt/mTOR signal pathway, was proven to have a close correlation with cognitive dysfunction such as in Alzheimer’s disease." (PMID 27116382, 2016).
Alzheimer disease (continued). "The mTOR signaling and Alzheimer disease-amyloid secretase pathways were significantly enriched for alerting, orienting and HRT respectively (FDR<5%)." (PMID 27656889, 2016). "In contrast, the other two pathways identified, the mTOR singalling pathways and the Alzheimer disease-amyloid secretase pathway involve processes of interest for cognition which, again involve AD." (PMID 27656889, 2016). "Functional importance of mTOR signalling has been experimentally confirmed in Alzheimer’s disease, and therapeutic targeting of this signalling module is considered as a promising strategy for developing neuro-protective treatments." (PMID 26379234, 2015). "Other reports also demonstrated that the mTOR signaling pathway has a significant function in neurodegenerative diseases, such as Alzheimer's disease, Parkinson's disease, Huntington's disease, and SCI." (PMID 26539474, 2015). "Actually, increased mTOR activity has been reported in cellular and animal models of Alzheimer's disease (AD) as well as in Huntington animal models and disease; inducing autophagy can also be beneficial in amyotrophic lateral sclerosis." (PMID 26474288, 2015). "For example, studies have shown that the mTOR inhibitor rapamycin reduces amyloid-beta levels, abolishes cognitive deficits in mouse models of Alzheimer's disease and suppresses brain aging in rats." (PMID 26142708, 2015). "These downstream elements of the mTOR signaling cascade are deregulated in the brain of Alzheimer’s disease patients well before the development of pathology." (PMID 24252508, 2013). "We have also examined the functional integrity of mTOR signaling in peripheral lymphocytes in Alzheimer’s disease patients relative to healthy controls." (PMID 24252508, 2013). "From interaction maps, we also found that genes in pathways involved in calcium, mTOR, Erbb signaling, and Alzheimer’s disease were significantly enriched." (PMID 23927422, 2013). "MTOR stimulates tau phosphorylation, potentially leading to Alzheimer's disease and other tauopathies." (PMID 23817674, 2013). "Blockade of mTOR signaling can impair long-term potentiation and synaptic plasticity in models of Alzheimer’s disease." (PMID 23109841, 2012). "In some experimental models of Alzheimer’s disease, neurons can be prevented from entering the cell cycle during the inhibition of mTOR and thus are protected from apoptosis." (PMID 23109841, 2012). "Recently it was shown that the mammalian target of Rapamycin (mTOR) pathway is involved in cellular senescence, organ aging and diseases of aging including Alzheimer's disease." (PMID 23211425, 2012). "We explored the relationship between the mTOR pathway and β-amyloid (Aβ)-induced synaptic dysfunction, which is considered to be critical in the pathogenesis of Alzheimer's disease (AD)." (PMID 20862226, 2010). "The fact that mTOR signaling pathways have had even greater enrichment of evolutionarily ancient genes with average values of PAI 2.29 indirectly supports the hypothesis of the link between mTOR and autism, and to a lesser extent Alzheimer’s disease." (PMID 41155356, 2025). "The present study evaluated whether inhibiting AMPK and activating mTOR could stop metformin from improving memory in rats with streptozotocin (STZ) -induced Alzheimer’s disease." (PMID 38333746, 2024). "Interestingly, Stanciu and colleagues have established that SGLT2 inhibitors are capable of repressing mTOR, which seems to bring benefits to patients with Alzheimer’s disease." (PMID 39158617, 2024). "In addition, mTOR is involved in neuronal development, synaptic plasticity, and cognition, and any deregulation in the mTOR signaling can be involved in brain pathologies such as Parkinson’s disease and Alzheimer’s disease." (PMID 39239097, 2024). "For example, FH may regulate or inhibit the mTOR pathway, and binds to apolipoprotein E (apoE), a major protein related to Alzheimer’s disease." (PMID 38799460, 2024).
Alzheimer disease (continued). "Given the PD-L1/PD-1, mTOR, and Wnt pathways play essential roles in the proper differentiation of cortical layers, cognitive development, brain injury, and Alzheimer’s disease, it is plausible that VSTM2A is indispensable in the maintenance of human central nervous system." (PMID 39289872, 2024). "In view of the fact that the hyperactivation of mTOR in patients with Alzheimer’s disease may impair autophagy, contributing to the accumulation of plaques and tangles, the dysregulation of autophagy is a key pathological feature of Alzheimer’s disease." (PMID 39203005, 2024). "In addition, the mTOR pathway appears to be a pivot that links cellular energetics and metabolism to both Alzheimer’s disease and type 2 diabetes (T2D)." (PMID 37919601, 2024). "Interestingly, the elimination of amyloid aggregates and p-tau in response to the activation of AMPK/mTOR pathway has been reported to improve cognitive deficits and neuropathology of Alzheimer’s disease." (PMID 38002000, 2023). "Inhibited autophagy by mTOR activation in Alzheimer’s diseases results in damaged cellular organelles such as mitochondria and accumulation of aggregated misfolded proteins which can cause inhibition of normal cellular processes and finally neuronal cell death." (PMID 37597078, 2023). "In addition, higher levels of mTOR activation—alongside its downstream effectors—were found in brain regions that were affected by Alzheimer’s disease or mild cognitive impairment." (PMID 36979330, 2023). "For example, it could prevent and treat Alzheimer's Disease by regulating the mTOR signal pathway, activating SIRT1, and deacetylating histone acetylases." (PMID 35932505, 2022). "Indeed, mTOR inhibition and autophagy activation have been shown to play a critical role in Alzheimer's disease." (PMID 36388931, 2022). "The mammalian target of rapamycin (mTOR) is a highly conserved serine-threonine kinase that is activated in response to various upstream signals such PI3K/Akt phosphorylation and mediates tau phosphorylation, representing a risk factor for Alzheimer's disease." (PMID 35746960, 2022). "Rapamycin, an inhibitor of mammalian target of rapamycin (mTOR), could restore cerebral blood flow via regulating NO release in Alzheimer’s disease mice." (PMID 34122022, 2021). "The top 20 significant terms of the KEGG analysis included endocytosis, Alzheimer's disease, the spliceosome, the mTOR signaling pathway, RNA transport, insulin resistance, autophagy, and the Notch signaling pathway, and these pathways were associated with HSF1." (PMID 34239690, 2021). "Pei J.J., Hugon J. mTOR-dependent signalling in Alzheimer’s disease.J." (PMID 34901706, 2021). "Flozins, by restoring the circadian rhythm of mTOR activity, seem to bring benefits in patients with Alzheimer’s Disease according to “Type 3 Diabetes Hypothesis”, “Mitochondrial Cascade Hypothesis” and “Endo-Lysosomal Dysfunction Hypothesis”." (PMID 34885795, 2021). "Cai Z., Chen G., He W., Xiao M., Yan L.J. Activation of mTOR: a culprit of Alzheimer’s disease?" (PMID 34901706, 2021). "Indeed, the mTOR pathway has been shown to be involved in many neurological disorders, such as autism spectrum disorders, Alzheimer’s disease, tuberous sclerosis complex, focal cortical dysplasia and, more recently, intractable epilepsy." (PMID 32157145, 2020). "Stimulating autophagy with mTOR inhibitors like rapamycin or its analogs had beneficial effects in fly and mouse models of Huntington’s disease, Alzheimer’s disease (AD), Parkinson’s disease (PD), frontotemporal dementia (FTD), spinocerebellar ataxia type 3 (SCA3) and prion disease." (PMID 30949479, 2019). "Interestingly, vascular mTOR-dependent mechanisms linking the control of aging to Alzheimer’s disease." (PMID 29802157, 2018).
Alzheimer disease (continued). "However; lithium's inhibition of GSK3B has also been postulated to have beneficial effects in Alzheimer's disease via reducing tau phosphorylation and neurofibrillary tangle formation as well as inhibiting autophagy via increasing mTOR signaling." (PMID 30425653, 2018). "Genes targeted and predicted to be targeted by the aging-dependent posttranscriptional regulation can be associated with biological processes known to play important roles in aging and lifespan extension, such as mTOR pathway, mitochondrial function and Alzheimer’s disease." (PMID 25853883, 2015). "In addition, inhibition of mTOR in murine models of Alzheimer’s disease can improve memory and reduce Aβ levels." (PMID 23109841, 2012). "Furthermore, activation of the mTOR pathway has shown to be involved in age-related diseases, such as Alzheimer's disease." (PMID 21931181, 2011). "Notably, lyso-ChR2 activation induces autophagy through the mTOR pathway, promotes Aβ clearance in an autophagy-dependent manner in cellular models, and alleviates Aβ-induced paralysis in the Caenorhabditis elegans model of Alzheimer’s disease." (PMID 38652732, 2024). "Furthermore, it suppresses mTOR expression, another crucial molecule in Alzheimer’s disease." (PMID 38338859, 2024). "Moreover, mitochondrial ATP synthase may be a potential drug target against aging, according to a study on the activation of the typical longevity AMPK/mTOR pathway in Alzheimer's disease." (PMID 36160705, 2022). "Moreover, chronic mTOR activation impairs lysosomal protein degradation, which supports the “Endo-Lysosomal Dysfunction” hypothesis of Alzheimer’s Disease." (PMID 34885795, 2021). "Similarly, KEGG enrichment analysis indicated that “PI3K-Akt signaling pathway,” “Endocytosis,” “MAPK signaling pathway,” “Alzheimer disease,” “mTOR signaling pathway,” “protein processing in endoplasmic reticulum,” and “Autophagy” were the most represented pathways." (PMID 34899276, 2021). "Several studies have revealed that mTOR signaling may be correlated to neurodegenerative diseases, including Parkinson disease, Huntington’s disease, Alzheimer’s disease." (PMID 33935683, 2021). "Similarly, the upregulated mTOR pathway has also been postulated in DS and may be a factor in the accumulation of cellular amyloid-β proteins contributing to the pathogenesis of Alzheimer's disease among DS cases." (PMID 33414730, 2020). "Trehalose, a naturally occurring disaccharide, has been proposed as an mTOR-independent autophagy enhancer and was reported to have therapeutic effects against atherosclerosis, myocardial infarction, spinal cord injury, traumatic brain injury, and Alzheimer's disease." (PMID 32117318, 2020). "Erk1/Erk2, members of the mitogen-activated protein kinase (MAPK) pathway, and Akt/mTOR, are important regulators of cell survival, proliferation and cell death and are involved in a wide range of disorders including cancer, vascular diseases, Alzheimer’s disease among others." (PMID 32001310, 2020). "Numerous studies link alterations of mTOR pathway to age-dependent cognitive decline and to pathogenesis of Alzheimer disease (AD), highlighting the importance of maintaining physiological levels of autophagy to promote neuronal health." (PMID 29888266, 2018). "Despite mTOR having a crucial role in integrating signals from energy homeostasis, metabolism, stress response, and cell cycle, its abnormal activation is also involved in other pathogeneses, such as Alzheimer’s disease, where it increases the development of amyloid beta (Aβ) and tau proteins." (PMID 30250008, 2018). "This could be particularly relevant for effects of rapamycin on cognitive aging and dementia, as numerous studies have shown that rapamycin and mTOR inhibition can delay cognitive decline during normative aging as well as prevent or reverse Alzheimer's disease progression in mouse models." (PMID 28919908, 2017).